CXCL13 (C-X-C motif chemokine ligand 13)
Diseases named in the same sentence as CXCL13 in open-access papers (continued):
Sharing a sentence is not in itself a finding about the gene and the disease.
tumor (continued). "Elevated levels of G-CSF, IL-6 and CXCL13, and B cell counts were associated with 4T1 growth, whereas CCL17, CXCL10, total myeloid cells, CCL2, IL-10, CXCL1, and Ly6Cintermediate monocytes were associated with CT26 tumour development." (PMID 35226704, 2022). "The gene CXCL13 was also a highly predictive gene marker in the whole tumor cohort." (PMID 35174087, 2022). "While our data need further validation from larger and independent BTC cohorts, they argue that CXCL13 levels might support the decision making of clinicians in terms of surgical tumor resection." (PMID 36077611, 2022). "CXCL13 was highly expressed in various tumor tissues and was also closely related to prognosis." (PMID 35141160, 2022). "CXCL10, CXCL13, and G-CSF were present at higher concentrations in the serum of tumor-bearing mice." (PMID 35013108, 2022). "Notably, CXCL13 secretion by polarized M2 macrophages can trigger the CXCL13/CXCR5/NFB/p65/miR-934 positive feedback loop in metastatic CRC tumor cells." (PMID 36348319, 2022). "In tumor microenvironments, tumor-infiltrating CXCL13-producing TFH cells may be involved in promoting local B cell localization, differentiation, and maturation." (PMID 35053457, 2022). "Moreover, murine Cxcl13 mRNA expression strongly correlated with human β2-microglobulin mRNA levels in BM (p < 0.0001 R2 = 0.64), indicating the interrelation between tumor burden and CXCL13 induction." (PMID 36217194, 2022). "Different cell types in the tumor milieu may overexpress CXCL13, including cancer cells, stromal and immune cells." (PMID 36217194, 2022). "Furthermore, CXCL13+CD103+CD8+ tumor-infiltrating T cells (TIL-Ts) were reported to correlate with B-cell recruitment in six cohorts of human tumors." (PMID 35967441, 2022). "Activated CD103+CTLs were involved in the migration of B cells to tumor via production of CXCL13." (PMID 35663939, 2022). "Analysis of the tumoral immune cell milieu revealed decreased frequencies of tumor-infiltrating CD8+ T cells on day 15 after i.t. artLCMV-TRP2 treatment in Cxcl13-Cre Il33fl/fl compared with Ctrl mice, whereas the abundance of other immune cell subsets was not substantially affected." (PMID 34354077, 2021). "This meta-analysis study revealed the importance of both tumor-cell-intrinsic (e.g., tumor mutational burden and PD-L1 expression) and tumor-cell-extrinsic (e.g., CXCL9, CD8A, CXCL13, CCR5 and T cell inflamed gene expression signature) factors underpinning ICB sensitization." (PMID 34092233, 2021). "Collectively, these findings support a chemoattractant mechanism for the sustained clinical response to pembrolizumab therapy observed in CTCL responders: upregulation of CXCL13 in tumor cells attracts effector PD-1+ CD4+ T cells, promoting successful antitumor activity." (PMID 34795254, 2021). "Additionally, the frequency of CXCL13-expressing cells was highest among tumor cells compared to other cell types." (PMID 34795254, 2021). "Chemokines, such as CXCL-13 and CXCL-5, can cause B cells to aggregate at the tumor site." (PMID 35087829, 2021). "Next, we assessed CXCL13 expression in tumor cells and its role in recruiting reactive lymphocytes." (PMID 34795254, 2021). "Moreover, microscopic analysis of IL-33-expressing cells in the TME of artLCMV-TRP2-treated Cxcl13-Cre/tdTom EYFP mice revealed cytokine-positive EYFP+ cells at the tumor margin." (PMID 34354077, 2021). "Recently, the role of CXCL13 in shaping the immunoactive tumor microenvironment has been confirmed." (PMID 34359579, 2021). "The CXCL13/CXCR5 axis shows anti-tumor and pro-tumor functions." (PMID 34947813, 2021). "We speculate that the increased RNA and protein expression of CXCL13 in responder tumor cells following pembrolizumab therapy is advantageous in localizing effector PD-1+ CD4+ T cells within the TME." (PMID 34795254, 2021).
tumor (continued). "Consequently, macrophages expressed higher amounts of the chemokine CXCL13, which can induce a positive feedback loop with tumor cells and enhance secretion of miR-934 through tumor-derived EVs." (PMID 34656117, 2021). "In addition, we found that increased CXCL10, CXCL11, and CXCL13 expression increased survival in patients with OC with tumor progression." (PMID 34794429, 2021). "Together, our data indicated that CXCL13 expression in the tumor microenvironment could significantly inhibit 4T1 tumor growth and mediate long-term protection against the parental tumor." (PMID 35693216, 2021). "CXCL13 might hinder tumor progression by increasing the number of immune cells at the tumor site which was evidenced by its correlation with greater prognosis and survival in multiple tumor types." (PMID 35058922, 2021). "In addition, the correlation between tumor tissue expressed CXCL13 and clinical survival was analyzed using the TCGA database." (PMID 35693216, 2021). "Subsequently, to assess whether the intratumorally expressed CXCL13 elicited a systemic antitumor immune response, a bilateral tumor inoculation model was established." (PMID 35693216, 2021). "In addition, these CXCL13-producing Tfh cells reverse Treg-mediated immune suppression and present adaptive anti-tumor humoral responses." (PMID 34947813, 2021). "The tumor growth curve was drawn based on the tumor size measurement during the animal experiment, which indicated that the chemokine CXCL13 could promote tumor growth and that A3149 could reverse the promotion of CXCL13 on tumor growth." (PMID 34922542, 2021). "Thus, a better understanding of the context-dependent functions of the CXCL13/CXCR5 axis in tumor tissue and the TME is required to design an efficient immune-based therapy." (PMID 34947813, 2021). "Both in vitro and in vivo experiments confirmed the original hypothesis that the overexpression of CXCR5 improves the migration of CAR-T cells to the CXCL13-positive tumor site, as shown directly by tracking CAR-T cells in vivo." (PMID 34553036, 2021). "Therefore, when considering the specific effect of CXCL13 in the tumor microenvironment, attention needs to be paid to the expression status of CXCR5 on cancer cells." (PMID 35693216, 2021). "On the other hand, chronic hypoxia may affect the expression of CXCL13 in the tumor indirectly—for example, via an increased expression of TGF-β in myofibroblasts in prostate tumors." (PMID 33467722, 2021). "The anti-tumor “N1” phenotype exhibited increased tumor cytotoxicity, elevated expression of CXCL13, CCL3, CCL6, CXCL10, TNFα and ICAM-1 and low ARG1 content, while the pro-tumor “N2” neutrophils expressed high levels of ARG1, MMP9, VEGF and several cytokines, including CCL2, CCL5, CCL17 and CXCL4." (PMID 34572138, 2021). "Thus, the Cxcl13-Cre/tdTom EYFP mouse model facilitates the phenotypical characterization of immune-stimulatory Cxcl13-expressing iCAFs in the TME and enabled the resolution of the molecular circuits underlying the artLCMV-induced activation of tumor FSCs." (PMID 34354077, 2021). "To confirm the reduced abundance of CXCL13+CD4+ T cells in EGFR-MT compared with EGFR-WT tumor, inferred from the single-cell transcriptome analysis, we performed the multiplexed immunofluorescence (IF) staining in archival tissue specimens of the same samples." (PMID 34663810, 2021). "In conclusion, our study provided evidence that CXCL13 expression in a mouse 4T1 tumor microenvironment triggered effective antitumor immunity by chemoattracting immune cell infiltrations, and CXCL13 could been considered as a novel prognostic marker for TNBC." (PMID 35693216, 2021). "CXCL13 research in RCC is mostly aimed at promoting tumor growth and evading immunity." (PMID 34922542, 2021). "In addition to potentiating tumor-stromal cell crosstalk, the CXCL13/CXCR5 axis exerts intracellular signaling cascade reactions, which are conducive to malignant cell survival and resistance to apoptosis." (PMID 34947813, 2021).
tumor (continued). "Interestingly, the chemokine (C-X-C motif) ligand 13 (CXCL13), which is also known as a ‘B lymphocyte chemoattractant,’ was highly upregulated in the tumor compared to normal lung in both macrophages, CD4+ and CD8+ T cells." (PMID 33918618, 2021). "In HEVhigh tumours compared with HEVlow tumours, gene profile of HEVs has shown upregulation of genes encoding lymphoid chemokines including chemokine (C-C motif) ligand (CCL) 19 (CCL19), CCL21, and CXCL13 as well as T-cell homing receptors (CCR7 and LSEL)." (PMID 33917287, 2021). "Tfh cells are found to produce CXCL13 that plays an immune-protective role in anti-tumor immunity." (PMID 34722522, 2021). "The expression of CXCL8, CXCL9, CXCL11, and CXCL13 was increased as the tumor stage increased." (PMID 33763130, 2021). "Likewise, analysis of genome-wide cDNA expression of tumor samples from ovarian cancer patients revealed that high CXCL13 correlated with better prognosis." (PMID 33193299, 2020). "CXCL13 has been found to act on cancer cells and potentially drive tumor progression." (PMID 33193299, 2020). "Therefore, this motivated an exploration into the role that B cells and their accompanying chemokine, CXCL13, play in tumor immunity across multiple tumor types." (PMID 33193299, 2020). "CXCL13 may hinder tumor progression by increasing the number of immune cells at the tumor site which is evidenced by its correlation with greater prognosis and survival in multiple tumor types." (PMID 33193299, 2020). "CXCL13-producing Tfh act as “organizers” of germinal centers in secondary and tertiary lymphoid organs, sustaining local humoral immunity by attracting antibody-secreting B cells, which control tumor progression." (PMID 33381121, 2020). "A new CXCL13+BHLHe40+ Th1‐like CD4+ subset was found to be present at higher proportion in MSI tumor and may explain higher IFN‐γ level in MSI tumor and better response of these patients to anti‐PD‐1 treatment." (PMID 32272497, 2020). "Therefore, CXCL13 likely plays an important role in immune cell infiltration, acts as a prognosis biomarker in patients with ccRCC and has potential role in tumor migration." (PMID 32669964, 2020). "B cells as well as CXCL13 play multifunctional roles in tumor immunity." (PMID 33193299, 2020). "In contrast, for CXCR5+ tumors, antibody blockade of CXCL13 may be a useful strategy for preventing CXCL13-driven tumor growth and invasion." (PMID 33193299, 2020). "To our surprise, we also found CCL5 and CXCL13 had the highest expression levels in tumor-associated T cells, which indicates that CCL5 and CXCL13 may play important roles in tumor immunity." (PMID 32549766, 2020). "In contrast, CXCL13 may contribute to a greater antitumor immune response through improving immune cell tumor infiltration." (PMID 33193299, 2020). "In the 4T1.2 triple-negative breast cancer (TNBC) mouse model, ILC3s are recruited to the primary tumors by CCL21 and stimulate tumor stromal cells to release CXCL13, leading to enhanced tumor cell motility, lymphangiogenesis, and lymph node invasion by tumor cells." (PMID 32117199, 2019). "Dissecting the molecular and signaling events regulated by CXCL13 and how this chemokine dynamically controls the interaction between the cancer cell and the tumor microenvironment is key to identify novel effectors and therapeutic targets for cancer treatment." (PMID 31354634, 2019). "Notably, CD4+ T cells with B cell-helper features, including high expression of PD-1, ICOS, and CXCL13, are enriched in multiple solid tumors and in murine tumor model, and these cells are preferentially expanded by anti-CTLA4 but not anti-PD-1 therapy." (PMID 30190721, 2018). "This raised the question of how PD-1++CXCL13+ cells act in the tumor environment." (PMID 30505306, 2018). "Therefore, in vivo experimental results also indicated that CXCL13 promoted androgen-dependent PCa cell growth and enhanced androgen-dependent subcutaneous xenograft tumor growth in nude mice." (PMID 28881808, 2017).
tumor (continued). "Furthermore, the expression of LT#βR-related chemokines, such as CCL21, CCL19 or CXCL13 increased in the EL4-Axl-tumor bearing mice compared to the mock control." (PMID 28423548, 2017). "IL-17A could promote the ESCC tumor cells to produce more chemokines CCL2, CCL20 and CXCL13, which were associated with the migration of B cells." (PMID 26942702, 2016). "Our results suggested that CXCL13 might induce the imbalance of different subclasses secreted by B cells and mediated immunomodulatory activities in tumor microenvironment." (PMID 26161394, 2015). "Elevated CXCL13 levels were associated with poor OS in patients with low tumor burden: those with non-detectable EBV or stages I/II." (PMID 25966773, 2015). "Production of CCL17, CCL1, chemokine (C-X-C motif) ligand-13 (CXCL13) and CXCL8 (IL-8) has been shown to be associated with the activation program for M2 tumor associated macrophage (TAM), and is parts of mononuclear phagocyte-mediated regulatory circuits of innate and adaptive immunity." (PMID 26172457, 2015). "Bindea and colleagues showed growth acceleration of MC38 isografts in Cxcr5−/− mice (CXCR5 is the receptor for CXCL13) compared to control, and rejection of tumour cells when recombinant CXCL13 was injected into the colonic submucosa of wild‐type mice before transplantation." (PMID 26115037, 2015). "Data from our lab suggests that the tumor is in fact capable of producing CXCL13 in some cases." (PMID 24762633, 2014). "Although increased immune cell infiltrate may be a positive prognostic marker in OSCC, the role of CXCL13 in this tumor microenvironment may be a double-edged sword." (PMID 24762633, 2014). "Categorizing tumors by the expression of either tumor-derived CXCL13, CCL19, CCL21, LTαβ or their key master regulators, such as the IRFs, may allow us to stratify patients more easily into IR+ or IR− subtypes." (PMID 24762633, 2014). "PCR-based approaches, such as combining analyses of a combination of mature FDC markers, HEV markers and TLS associated chemokines such as CCL19, CCL21 and CXCL13, could also decrease the chance of missing TLS-positive tumours." (PMID 25177210, 2014). "However, the animals that developed R- or BCBL-1-derived tumors (n = 2 /group) all showed greatly elevated serum levels of murine CXCL13 (ranging from about 10,000 to 40,000 pg/ml), and in tumor ascites fluid (ranging from about 25,000 to 100,000 pg/ml)." (PMID 23936541, 2013). "Interestingly, both primary tumors (shown) and metastases (not shown) all contained what appeared to be infiltrating, macrophage-like non-tumor cells that strongly stained positive for murine CXCL13." (PMID 23936541, 2013). "Clearly, though, further studies will be needed to more precisely determine the role that CXCR5 and CXCL13 may be playing in tumor growth." (PMID 23936541, 2013). "Further studies are needed to definitively identify the actual mouse cells producing murine CXCL13 in this model, since the CXCL13(+) tumor-infiltrating cells might merely be binding circulating chemokine, which is present at very high levels." (PMID 23936541, 2013). "One might imagine at least three possible ways for CXCL13 to mediate a promoting effect on tumour development, the first two of them involving cellular immunity." (PMID 18781150, 2008). "Another possibility might be that CXCL13 mediates some form of protection against immune-mediated anti-tumour immunity." (PMID 18781150, 2008). "In contrast, immune changes following anti-PD-1/PD-L1 therapy have been extensively analyzed in patient tissues, highlighting the roles of regulatory T cells and CXCL13 + T cells, though their precise localization and function within the tumor microenvironment (TME) remain unclear." (PMID 40670667, 2025).
tumor (continued). "Additionally, co-occurrence of tumor-associated CD8+ T cells and CD20+ B cells improves survival in metastatic melanoma patient samples, where TLS in CD8+CD20+ tumors stained for CXCL13, CXCR5, and CD20, and B cell-enriched tumors had increased TCF-7 naive and/or memory T cell levels." (PMID 40475770, 2025). "In addition, CXCL13 is present with neutrophils in the tumor." (PMID 40647506, 2025). "Collectively, these findings suggest that while CXCL13 may selectively enhance B cell recruitment under conditions that preserve B cell populations, its influence on endogenous T cells and macrophages appears limited in the tumor models tested." (PMID 40492496, 2025). "We have previously shown that tumor-infiltrating T cells expressing a TCR against a tumor-specific neoepitope in a vaccinated patient with glioma could be distinguished from bystander T cells on the basis of their expression of CXCL13 and CD40LG15." (PMID 38454173, 2025). "In addition to exerting anti-tumor functions through immunomodulatory effects on the TME, studies have reported that CXCL13 may directly affect tumor cells." (PMID 40406143, 2025). "Therefore, the observed increase in CXCL13+CD8+ T cells in the PPCT-P group suggests that anti-PD-1 blockade when combined with nCRT may drive the expansion of tumor-specific CD8+ T cells." (PMID 41309527, 2025). "These CXCL13+CD8+PD-1+TIGIT+ T cells, referred to as effector-like CD8+ Tex cells, are characterized by robust cytotoxicity, secretion of inflammatory cytokines and chemokines, and strong association with antitumor immune responses, suggesting their involvement in effective tumor control cells." (PMID 40799645, 2025). "To assess whether CXCL13 might recruit B cells into the tumor—given their essential role in tertiary lymphoid structure (TLS) formation —we generated a new CXCL13‐overexpressing CAR T cell targeting Claudin 18.2 (CLDN18.2), thereby preserving endogenous B cells." (PMID 40492496, 2025). "Moreover, a meta-analysis also demonstrated that CXCL13+ T cells could be tumor-reactive T cells to ICIs in the treatment of multiple solid tumors." (PMID 38478516, 2024). "CD4-C4 distinguished by high CXCL13 expression level were identified as CXCL13+ follicular helper T cells, which have been reported to regulate B cell chemotaxis and play a critical role in transitioning from Treg-mediated immune suppression to adaptive anti-tumor humoral responses." (PMID 39232806, 2024). "In addition, markers increasing from baseline in patients progressing through treatment include CXCL13, CCL17, and reduced clonal T-cell diversity, likely reflecting increasing tumor burden and activation of a Tfh axis previously associated with poor prognosis of lymphocyte-rich HL." (PMID 38934093, 2024). "However, we found a greater density of CXCL13+ cells in TLSs compared to the tumor (CXCL13_TLS/CXCL13_T ratio, p = 0.031) in responders vs. non-responders, which is believed to be influenced by interaction between CXCL13+ and CD20+ cells within the TLS compartment." (PMID 38398098, 2024). "Moreover, inducing the formation of TLS, like by intratumoral injection of vital cytokines such as CXCL13, administration of engineered cells and tumor vaccines, may provide a neoteric perspective for synergistic immunotherapeutic method." (PMID 38519621, 2024). "Notably, re-emerged clonotypes in ISG-15+CD8+ T cells after treatment among EBV (+) patients were detected and associated with effector T population expressing CXCL13 in responsive EBV (+) tumor, indicating their significant importance in tumor immunochemotherapy response." (PMID 39334490, 2024). "Our analyses showed that CD8+ T cells, which are directly associated with tumor immunotherapy response, as well as T cells were more highly expressed at higher levels of all four molecules; B cells were also more highly expressed at higher levels of XCR1, CCR10, CXCL13, CXCR6." (PMID 39835121, 2024).